INS (insulin)
Diseases named in the same sentence as INS in open-access papers (continued):
Sharing a sentence is not in itself a finding about the gene and the disease.
diabetes (continued). "By limiting lipolysis, insulin plays an essential role in preventing diabetic ketoacidosis while also mitigating the harmful lipotoxic effects of excess NEFAs on lean tissues, which contribute to diabetes-related complications." (PMID 40725728, 2025). "Specifically, in the 1990s carbohydrate counting (CC, i.e., counting the number of carbohydrates found in food and using this value to estimate prandial insulin needs) became a topic of interest in the US, solidified with the Diabetes Control and Complications Trial results." (PMID 41244048, 2025). "Upgrading the expression of PPARγ enhances lipid metabolism and insulin sensitivity in diabetes." (PMID 40843204, 2025). "Patients with diabetes usually take medications to control blood glucose levels, such as insulin, biguanides, or sulfonylureas, which not only directly affect glycemic regulation, but may also affect lipid levels." (PMID 40670519, 2025). "We show that basal insulin hypersecretion is a modifiable, causal driver of liver fat accumulation, particularly in individuals without diabetes." (PMID 40502600, 2025). "Despite advancements in diabetes care, including the development of insulin analogs, continuous glucose monitoring, and automated insulin delivery systems, type 1 diabetes remains a condition that imposes significant medical, psychological, and socioeconomic burdens on affected individuals." (PMID 41036118, 2025). "Insulin pump users also require education on managing acute issues such as pump site failure and hyperglycemia, and therefore, a pump safety action plan provided during our prepump and postpump visits likely helped mitigate pump-related diabetes emergencies." (PMID 40110444, 2025). "In addition, we examined the prevalence of sarcopenia in patients with diabetes according to disease duration and insulin use." (PMID 41464593, 2025). "Similarly, where diabetes management used to be relatively simple, with limited treatment options (basically ‘only’ sulphonylureas, metformin, or insulin), there is increasing evidence that additional subtypes of diabetes now exist." (PMID 40478782, 2025). "However, the standard therapeutic approaches for diabetes, including insulin therapy and oral hypoglycemic medication (metformin and glibenclamide), present significant challenges." (PMID 40243881, 2025). "This may be observed during the development of pre-diabetes and diabetes, when pancreatic β-cells produce more insulin, compensating for IR." (PMID 40565151, 2025). "These substances could enhance the body’s response to insulin and have antioxidant effects, offering properties that support the management of diabetes." (PMID 41011114, 2025). "Clinical characteristics, including mean diabetes duration and insulin use, were similar." (PMID 40822958, 2025). "Finally, we examined the expression of PIK3R1, TPK1, and IPMK in blood samples from 20 people with diabetes before and after intensive insulin therapy." (PMID 40299682, 2025). "Additional investigations have examined the antidiabetic properties of lupeol derived from Solanum xanthocarpum, which demonstrated its capability to impede the progression of diabetes by reducing glucose levels, lowering nitric oxide, increasing serum insulin, and enhancing antioxidant levels." (PMID 39943031, 2025). "Additionally, LXRs enhance insulin sensitivity and influence β-cell function, presenting potential benefits for diabetes management." (PMID 40926269, 2025). "Additionally, it decreased hemoglobin A1c, increased insulin sensitivity, and improved fasting blood glucose levels, suggesting potential benefits for people with diabetes and metabolic syndrome." (PMID 40278218, 2025). "Indeed, both animal and clinical trials on diabetes have confirmed that activation of the AKT pathway participates in topical insulin-induced wound healing." (PMID 39923118, 2025). "The search strategy combines three key concepts: diabetes, insulin, and biosimilars." (PMID 40737300, 2025).
diabetes (continued). "Furthermore, in genetically compromised KK-Ay mice, which acquire diabetes and exhibit hyperglycemia with aging due to resistance of insulin, 4-hydroxyderricin (0.15%) also reduced the progression of diabetes." (PMID 40599794, 2025). "In this review, we discussed the role of miR-22 in metabolic diseases such as MASH, obesity, and diabetes, implicating its function in altering gluconeogenesis, thermogenesis, the browning of adipocytes, insulin sensitivity, glucose homeostasis, fatty acid biosynthesis, and lipid catabolism." (PMID 39859495, 2025). "However, standard therapeutic approaches for diabetes, including insulin therapy and oral hypoglycemic medicines (metformin and glibenclamide), present significant challenges." (PMID 40243881, 2025). "Chronic low-grade inflammation is considered an important mechanism for the occurrence and progression of diabetes, possibly by weakening the insulin sensitivity of insulin target tissues (such as adipose tissue, muscle, and liver), leading to insulin resistance (IR)." (PMID 41040857, 2025). "Supporting PWDI to provide sufficiently detailed information about their insulin and diabetes management in a format healthcare professionals can access could reduce the information gap during ToC." (PMID 40324886, 2025). "While these strategies remain speculative, further elucidation of Cav-1’s role in insulin signaling may pave the way for novel therapeutic approaches to diabetes and related metabolic disorders." (PMID 40243482, 2025). "Somatostatin from pancreatic δ‐cells is a paracrine regulator of insulin and glucagon secretion, but the release kinetics and whether secretion is altered in diabetes is unclear." (PMID 39803760, 2025). "In such contexts, where the burden of diabetes is high, and continuous IV infusions may be logistically challenging or costly, the programmatic implementation and safety of using SC insulin are critical considerations." (PMID 41227190, 2025). "Patients with diabetes using insulin,diagnosed in the last six months." (PMID 41379990, 2025). "For instance, in diabetes, abnormal m6A modifications on the mRNA of genes involved in key metabolic pathways may lead to changes in the expression of proteins related to insulin secretion, subsequently affecting blood glucose metabolism." (PMID 40066222, 2025). "Diagnostic criteria for LADA are the following: adult-onset DM (>30 years at diagnosis), presence of autoantibodies associated with diabetes, and no requirement for insulin for least 6 months after diagnosis." (PMID 39859258, 2025). "In thepresent case, MASLD and diabetes characterized by impaired insulin secretionwere observed." (PMID 40840513, 2025). "First, during the pandemic, severe limitations in access to and utilization of healthcare services—including insulin and other medications, as well as blood glucose and renal function monitoring—led to disruptions in medical care for patients with preexisting diabetes." (PMID 40814743, 2025). "Early diabetes stage, no use of insulin, younger age and achieving a total body weight loss of more than 20 % after surgery are all known predictors for diabetes remission." (PMID 40740163, 2025). "This multi-modal action could complement SGLT2 modulation by addressing the complex pathophysiology of diabetes beyond direct glucose reabsorption inhibition, for example, by reducing systemic inflammation or improving insulin sensitivity." (PMID 40872492, 2025). "Furthermore, TyG, Insulin therapy, HbA1c, and Diabetes course showed positive effects on retinopathy, while HDL showed negative effects." (PMID 41293734, 2025). "Here, we examined the association of plasma sphingolipids with insulin sensitivity and secretion in people without diabetes." (PMID 40630937, 2025).
diabetes (continued). "Significant differences were observed in statements Q2, Q3, and Q5, which relate to emotional impacts of diabetes, as well as in Q10, “I am tired of trying to figure out my insulin dose at every meal”, and Q16, “I am annoyed by having to rotate injection sites or pump infusion sites”." (PMID 39860531, 2025). "Reduced PAX4 expression in hPS cells may affect their differentiation into insulin-producing β-cells negatively, which could be crucial for diabetes studies." (PMID 40666289, 2025). "Furthermore, diabetes is known to disrupt bile secretion and metabolism, such as through impaired insulin-mediated bile signaling, leading to bile composition changes that increase gallstone risk." (PMID 39944962, 2025). "In any case,recent advances in electrically stimulated insulin delivery systemshighlight the interest in electrosensitive materials to regulate therelease of this drug more quickly and with greater dose control, thusachieving more efficient diabetes therapy." (PMID 40978378, 2025). "Anxious individuals, intensely dedicated to diabetes management, emphasized functionalities like first alert delay, adjustable hyperglycemic thresholds, especially in the postprandial context, and suitable recommendations for insulin dose adjustments." (PMID 40181799, 2025). "Patients with diabetes exhibit an impaired counterregulatory response to hypoglycemic events, such as a suboptimal release of glucagon, cortisol, and epinephrine, which stimulate glycogenolysis and gluconeogenesis and inhibit insulin secretion." (PMID 39913488, 2025). "The metabolism of glucose is affected due to a lack of insulin or its impaired function which raises the blood glucose level, and causes diabetes." (PMID 40019907, 2025). "During the early stages of type 1 diabetes mellitus (T1DM), the seroconversion of islet-specific autoantibodies—targeting insulin, glutamate decarboxylase, insulinoma-associated antigen 2, or zinc transporter 8—represents the earliest notable indicator of autoimmune activity." (PMID 40430501, 2025). "Although the risk of hypoglycemia decreases with advanced diabetes technologies, we were unable to show any association between FoH and type of insulin administration (automated insulin delivery systems were not available when our study was conducted)." (PMID 41212850, 2025). "One underlying mechanism might be the development of vascular insulin resistance as a key feature of diabetes, characterized by impaired insulin-induced vasodilation leading to endothelial dysfunction." (PMID 41373661, 2025). "In this mechanism, insulin undergoes two phases in terms of its secretion in response to glucose administration: an acute phase in which there is a substantial reduction in insulin secretion for several minutes, and a phase in which diabetes is already diagnosed." (PMID 41020831, 2025). "This study demonstrated an improved reduction in plasma glucose levels and a marked increase in blood insulin concentrations at 20- and 135-min after oral insulin administration, when co-administered with a peptidase or proteinase inhibitor, in both lean and obesity-induced diabetes rat models." (PMID 41477339, 2025). "For instance, the impact of OSA may differ between early-stage diabetes and long-standing or insulin-treated cases." (PMID 40565914, 2025). "Furthermore, GPCRs are involved in regulating insulin sensitivity, which is crucial for maintaining metabolic homeostasis and preventing conditions such as diabetes." (PMID 40860192, 2025). "Notably of course if this is T1DM, or diabetes secondary to pancreatic disease, then uninterrupted insulin dosing will be required for life (together with reassurance as to how this can deliver a long and healthy life)." (PMID 40035222, 2025). "In diabetes, insulin dysfunction results in the increased cholesterol and triacylglycerols." (PMID 41030912, 2025).
diabetes (continued). "A deeper understanding of amino acid transporters’ roles in metabolic processes and insulin signaling could shed light on the pathogenesis of diabetes and unveil novel therapeutic targets for this pervasive metabolic syndrome." (PMID 40469683, 2025). "CP may be considered a severe condition compared to diabetes, as children with diabetes may rely on insulin to stabilize their conditions." (PMID 40658362, 2025). "Some of the benefits of smart insulin are reducing the need for frequent injections, improving glycemic control by minimizing hyperglycemia and hypoglycemia risks, and lowering the likelihood of long-term diabetes-related complications." (PMID 40217595, 2025). "This review aims to update the general physicians with diabetes technologies such as continuous glucose monitors, insulin pumps, hybrid closed loop systems and how to troubleshoot in acute illnesses, diabetes emergencies, perioperative management and radiological investigations." (PMID 41354385, 2025). "Notably, among participants with diabetes, insulin use was more frequent in the LC group (28%, 15/53) compared to the recovered group (7.6%, 1/13; data not shown)." (PMID 41459516, 2025). "Being on treatment with both oral hypoglycemic agents (OHA) and insulin, having a diabetic foot ulcer, and not having adequate physical activity were found to be significantly associated with diabetes distress." (PMID 41523497, 2025). "While the continuous subcutaneous insulin infusion provides significant advantages in diabetes treatment, it may lead to eating disorders." (PMID 41010976, 2025). "Considering the skeletal muscle is a major site for insulin‐stimulated glucose disposal, the impact of myosteatosis on muscle function may vary depending on diabetes." (PMID 40035123, 2025). "The findings suggest that CHM may enhance glycaemic control by supporting β-cell function and improving insulin sensitivity, although its role in severe diabetes remains limited." (PMID 41552833, 2025). "The fact that a diagnosis of diabetes < 5 years prior to the study was the strongest predictor of HbA1c reduction further highlights the need for an early proactive intervention, when beta-cell function and insulin resistance are still adjustable." (PMID 40573252, 2025). "Diabetes mellitus (DM) is a chronic metabolic condition characterized by hyperglycemia resulting from defects in insulin secretion, insulin action, or both, can leads to severe damage to the heart, blood vessels, eyes, kidneys, and nerves over time, if not treated properly." (PMID 40529214, 2025). "Consequently, elevated blood sugar levels ensue, prompting heightened insulin secretion and culminating in the progression towards diabetes." (PMID 39761309, 2025). "Diabetes mellitus type 2 develops with a resistance to insulin action." (PMID 39905472, 2025). "A deeper examination of pancreatic β-cell function (e.g., insulin secretion dynamics and islet morphology) could further clarify O3’s role in diabetes pathogenesis." (PMID 40863931, 2025). "Initial assessment should include a review of the diabetes and insulin history." (PMID 40746499, 2025). "Importantly, our large cohort study demonstrates that metformin reduces viremia and SFTSV-related mortality in patients with hyperglycemia or pre-existing diabetes, contrasting with the disadvantageous effect of insulin." (PMID 40391966, 2025). "Moreover, it is proposed that β-cell deterioration in T2D is associated with both mitochondrial dysfunction and redox imbalance, affecting proinsulin maturation and insulin granule stores, contributing to diabetes progression." (PMID 40109403, 2025). "Type 1 diabetes mellitus (T1DM) is an autoimmune condition marked by the inadequate production of insulin due to the T-cell-driven destruction of pancreatic beta cells that secrete insulin." (PMID 40904962, 2025).
diabetes (continued). "Because of the potential for diabetes-related neuropathy or the effects of a high dose of fennel leaf extract, there may be an imbalance between insulin and C-peptide ratios." (PMID 40518509, 2025). "The liver is one of the insulin-sensitive tissues most adversely affected by diabetes." (PMID 40806520, 2025). "Also an alginate graphene oxide hydrogel supports encapsulated pancreatic β cells, enhancing viability, proliferation and insulin secretion while offering a compact, low swelling matrix suitable for in vitro diabetes treatment studies." (PMID 41294602, 2025). "Finally, clinicians using insulin analogs or any diabetes medication for their patients should recall that beta-blockers can mask symptoms of hypoglycemia." (PMID 40156735, 2025). "Though identified before insulin, phlorizin was limited as a diabetes treatment because of its poor oral absorption and its effects to reduce intestinal glucose absorption that causes diarrhea through nonselective inhibition of SGLT1 which is prominently expressed in the gut lumen." (PMID 39950157, 2025). "Other subsequent trials of GGE in similar populations of adults without diabetes have demonstrated equally intriguing effects on weight loss, improved insulin resistance, and reduced glycemic variability." (PMID 40338170, 2025). "Effective diabetes management is crucial, as patients with diabetes are responsible for making most of their own health decisions, including dietary choices, physical activity, blood glucose monitoring, carbohydrate counting, and insulin dosage adjustments." (PMID 40310669, 2025). "Moreover, the level of insulin presentation during thymic T cell education affects diabetes rate and onset in the NOD model." (PMID 39600694, 2024). "Thus, the mice that developed diabetes through HFD/STZ exhibited worsened lipid metabolism due to decreased insulin secretion capacity." (PMID 39479116, 2024). "For example, in a system recommending treatment for diabetes, the system may recommend – based on coded electronic data – that it is appropriate to start insulin; though after considering patient context and wishes the clinician may choose to override this." (PMID 38646041, 2024). "Due to the tightly intertwined connection between the insulin resistance pathway and the PI3K/AKT signaling pathway, regulating the PI3K/AKT pathway and its associated targets is essential for hypoglycemia and the prevention of type 2 diabetes mellitus." (PMID 38799166, 2024). "Diabetes, an endocrine and metabolic disorder impacting over 400 million individuals globally, is characterized by compromised pancreatic beta-cell functionality, insufficient insulin secretion, or insulin resistance." (PMID 39682954, 2024). "An intervention involving insulin administration was required by group 2 participants with pre-existing diabetes within six hours of steroid administration, followed by those with gestational diabetes requiring intervention within 12-24 hours, and by group 1 participants at 24-48 hours." (PMID 38854292, 2024). "High-scoring patients were also less likely to rely on insulin to manage diabetes pre-surgery, which may reflect the duration or severity of their condition." (PMID 39174748, 2024). "This designation meant that an ACE insulin pump could be used with different components that make up diabetes therapy systems." (PMID 38041737, 2024). "Furthermore, sarpogrelate and insulin treatments were observed to partially or fully attenuate diabetes-induced alterations in both SR and MF activities." (PMID 39057635, 2024). "The inverse association of serum Mg2+ with insulin levels is found in people with and without diabetes." (PMID 38279093, 2024). "However, individuals with diabetes mellitus (DM) experience elevated blood sugar levels due to insulin dysfunction or resistance, impairing glucose uptake by cells." (PMID 39091901, 2024).